NANOG (Nanog homeobox)
Diseases named in the same sentence as NANOG in open-access papers (continued):
Sharing a sentence is not in itself a finding about the gene and the disease.
cancer (continued). "We demonstrated that the hypoxia inducible factor (HIF-1α) is present in cancer stem cells as well in differentiated cancer cells, while cancer stem cells express NANOG, which is a stem cell marker." (PMID 30424475, 2018). "Stem cell‐associated genes are highly expressed in CSCs, and activation of stem cell‐associated pathways (such as Wnt/β‐catenin, NOTCH, NANOG, and SHH/GLI) promotes the CSC phenotype in cancer cells." (PMID 28453235, 2017). "In immunohistochemistry, NANOG is usually detected in the nuclei, but MK is mainly localized in the cytoplasm of pluripotent stem cells or cancer cells." (PMID 29113102, 2017). "In particular, enhanced co-localization of MK and NANOG proteins was usually detected in the cancer cells of high-grade tumors." (PMID 29113102, 2017). "In fact, the pluripotent cell markers OCT4, SOX2, Klf4 and NANOG have been shown to be expressed in certain cancer cell types and to play an important role in oncogenesis." (PMID 28103575, 2017). "In cancers where aberrantly reactivated, SALL4 has been associated with the expression of many stemness-related genes (i.e. OCT4, NANOG, c-Myc, and SOX2) conferring to the cancer cells self-renewal pluripotency abilities." (PMID 28160555, 2017). "We suggest that bigger NANOG-and vimentin-positive round cells with large nuclei that separated from surface epithelium represent putative cancer stem cells (CSCs) which arise in the EMT process." (PMID 28231820, 2017). "More importantly, strong cytoplasmic NANOG protein expression (score 2) significantly correlated with higher cancer incidence in both patient cohorts." (PMID 28894270, 2017). "In pretreatment biopsy specimens of OSCC, NANOG was mainly detected in the nuclei of OSCC cells, but some NANOG expression was detected in the cytoplasm of cancer cells." (PMID 29113102, 2017). "OCT-4, NANOG and SOX-2 contribute to the hallmark characteristics of stem and putative cancer stem cells by activation of target genes that encode pluripotency and self-renewal mechanisms." (PMID 29238047, 2017). "It’s worth noting that some cancer stem cell factors, such as Nanog homeobox (NANOG), are well-known targets of STAT3 signaling pathway, further elucidating the regulatory role of STAT3 signaling in the maintenance of CSCs." (PMID 28750679, 2017). "The F3.EGFRviii cell line was highly tumorigenic in vitro and showed high ERK1/2 activity as well as expression of a variety of genes associated with cancer stemness, such as SOX2 and NANOG, under spheroid culture conditions." (PMID 28830458, 2017). "In serial sections of high-grade OSCC specimens, MK and NANOG proteins showed highly similar expression patterns, in which they were negatively expressed in interstitial tissue and strongly expressed in cancer tissues and cells." (PMID 29113102, 2017). "The pluripotency transcription factor (TF) NANOG is aberrantly expressed in a spectrum of cancers, including germ cell tumors and cancers of the brain, head and neck, colon, breast, ovary, liver and prostate, among others." (PMID 27867534, 2016). "Recently, it was reported that NANOG plays an essential role in adult cell reprogramming, malignant cell transformation and cancer initiation, while OCT4 and SOX2 are dispensable; however, these reports did not distinguish between NANOG1 and NANOGP8." (PMID 28033430, 2016). "Nevertheless, NANOG promoter binding in LNCaP cells is largely distinct from that in ESCs, forecasting potentially fundamental differences in NANOG functions in somatic cancer cells vs pluripotent cells." (PMID 27867534, 2016). "Strong experimental and correlative clinical evidence suggests that NANOG (NANOG or NP8) is expressed in subpopulations of cancer cells and has functional roles in mediating CSC properties, cell motility and invasion, therapy resistance, and metastasis." (PMID 27867534, 2016).
cancer (continued). "As already mentioned, certain phenotypic characteristics are shared by ES cells and some aggressive cancer cells, such as unlimited self-renewal and expression of some pluripotent genes (NANOG, OCT4, SOX2)." (PMID 27460364, 2016). "NANOG is an ESC transcription factor and its expression has been associated with multiple types of cancer, including those affecting the lung, oral cavity, breast, and prostate." (PMID 27148537, 2016). "We therefore performed Q-PCR and found that drug treatment upregulated the expression of these cancer stem cell-associated genes in all three cell lines, including ALDH1, SOX2, c-MYC, OCT4, and NANOG." (PMID 26506421, 2016). "We observed the highest NANOG/P8 expression in sphere cells derived from poorly differentiated cancer cell lines (MGC-803, MKN45) and lower NANOGP8 expression in moderately differentiated cell lines (SGC-7901)." (PMID 28033430, 2016). "Conversely, NANOG overexpression promotes CSC traits in many cancer cells and, importantly, castration-resistant tumor development in androgen-sensitive LNCaP PCa cells." (PMID 27867534, 2016). "In summary, we demonstrate in vivo that NANOG has oncogenic potential to induce skin SCCs and this occurs in association with NANOG-dependent induction of an EMT program and cancer stem features." (PMID 25988972, 2015). "These cells are often termed cancer stem-like cells (CSCs) and express pluripotency-related genes, such as NANOG, OCT3/4, and SOX2, which are essential transcription factors in embryonic stem cells (ESCs)." (PMID 26087476, 2015). "First, pseudogenes often show cancer-specific deregulated expression, for example in the case of the OCT4 and NANOG pseudogenes, which are aberrantly expressed in cancer cells instead of their parental genes." (PMID 26442270, 2015). "Embryonic stem cells rapidly progress through the cell cycle without checkpoints, and many components of the core embryonic stem cell machinery – SOX2, OCT4, NANOG, and c-Myc – are expressed and active in cancer stem cells." (PMID 25938542, 2015). "NANOG1 and NANOGP8 overexpression increases drug resistance in cancer cells, and NANOG knockdown increases drug sensitivity in cancer cells." (PMID 26087476, 2015). "Our findings suggest that the malignant potential of cancer cells is increased by NANOG protein expression from both NANOGP8 and NANOG1." (PMID 26087476, 2015). "NANOG was mainly detected in the nuclei of OSCC cells, but some NANOG expression was detected in the cytoplasm of cancer cells." (PMID 26626427, 2015). "Recent studies revealed that NANOG is highly detected in poorly differentiated carcinomas and late-stage tumors." (PMID 26626427, 2015). "Our results show that the nuclei of cancer cells in the majority of OSCC samples (86.7%) were NANOG-positive." (PMID 24348816, 2014). "Consistent with the cancer stem cell phenotype, we also found that the rolling PC-3 cells express higher levels of stem cell markers, such as NANOG, CD133, CK 5, and prostate specific stem cell marker (PSCA) compared to floating PC-3 cells by QPCR." (PMID 25301730, 2014). "Although studies investigating the function of NANOG in cancer have shown that it plays several roles, such as in cell proliferation, invasion and metastasis, the overall function of NANOG in cancer cells has remained elusive." (PMID 24348816, 2014). "The results of the present study demonstrate that undifferentiated cancer cells overexpressing NANOG are important for metastatic OSCC." (PMID 24348816, 2014). "Here, we investigated the epigenetic regulation of pluripotency-associated genes NANOG, OCT4, c-MYC, KLF4, and SOX2, and their correlation with gene expression in cancer cell lines and primary tumor samples." (PMID 24023739, 2013). "Activation of the molecular targets of pluripotency-associated genes (NANOG, OCT4, SOX2, and c-MYC) is frequently observed in poorly differentiated cancers." (PMID 24023739, 2013).
cancer (continued). "Our observation of OCT4/NANOG cross-induction in HCT116 cells further demonstrates a conservation of cross-regulatory function between pluripotent factors in cancer cells." (PMID 24023739, 2013). "This suggests that the pluripotency regulatory circuit is conserved in cancer cells and it is partially restored in cancer cells via the epigenetic mechanism that reprograms NANOG promoter methylation." (PMID 24023739, 2013). "This provides strong in vivo evidence to support the function of NANOG in promoting cancer cell metastasis." (PMID 24023739, 2013). "Following the identification of NANOG upregulation in metastatic HCC cells and tumor samples, we furthered our study to examine the in vivo function of NANOG in cancer progression." (PMID 24023739, 2013). "RNA interference-mediated NANOG knockdown inhibited tumor development in xenograft animals and decreased long-term clonal and clonogenic growth of cancer cells." (PMID 23662114, 2013). "Immunohistochemical analysis of tumor xengrafts further confirmed that NANOG overexpression enhanced tumor development and increased expressions of cancer stemness protein-SOX2 and MUC1 in tumor xengrafts." (PMID 23662114, 2013). "Recent work has shown that NANOG was functionally involved in human tumor development and in regulating cancer stemness." (PMID 23662114, 2013). "Cancer cells from other tissue origins displayed differential NANOG promoter methylation; for example, hypomethylation was observed in HeLa (25%), whereas hypermethylation was shown in MCF7, HCT116 and AGS (71%, 92% and 91%, respectively)." (PMID 24023739, 2013). "In contrast, some Dox-treated cancer cells still expressed NANOG which can explain how tumors can still be slightly propagated." (PMID 23662114, 2013). "Real time RT PCR analysis indicates higher expression of pluripotency markers OCT4 and NANOG, and cancer stem cell markers CD133 and ALDH1 in SP fractions compared to non-SP (NSP) fractions in both DU145-TXR and PC3-TXR cells." (PMID 22768203, 2012). "NANOG and POU5F1 are well-known transcription factors that play critical roles in maintaining the pluripotency of embryonic stem cells, and their expression has been associated with poor prognosis in various cancers, including PDAC." (PMID 40699634, 2025). "OCT4 (POU5F1), SOX2, and NANOG were expressed at higher levels in cancer cell lines than in MSCs." (PMID 39621192, 2025). "Examples include overexpression of the pluripotency- and apoptosis-related POU5F1 (OCT4) (i.e., TGCT-15.6.3.P.3.0.0.2.4.2), SOX2 (i.e., LUSC-2293.6.3.P.3.62.30.1.4.3), and NANOG (i.e., TGCT-4.6.3.P.3.0.0.2.4.1) genes in various cancer types associated with stemness and poor prognosis." (PMID 41048343, 2025). "SOX2 and NANOG, key transcription factors in cancer stem cell biology, may drive tumor progression and therapy resistance." (PMID 40227667, 2025). "NANOG, a homeobox transcription factor essential for maintaining the pluripotency of Embryonic Stem Cells (ESCs), plays a critical role in tumorigenesis, progression, and metastasis in a variety of human cancers." (PMID 41465103, 2025). "Current cancer chemotherapy uses etoposide to induce DNA double-strand breaks for cell killing, which can cause fluctuations in stemness promoters like OCT4A, SOX-2, or NANOG in relation to senescence promoters p21Cip1, p27, or p16ink4A, and mitigate anti-cancer therapy." (PMID 40805179, 2025). "Additionally, the high expression of cancer stem cell markers such as SOX2 and NANOG has been implicated in tumorigenicity and metastasis." (PMID 40626009, 2025). "However, NANOG expression is detectable in a small proportion of cancer cells that show stem cell-like properties." (PMID 38558704, 2024).
cancer (continued). "The analysis of the tumoral markers p27, CD44, Fibulin-3, and NANOG and the expression of genes related to cancer transformation such as NANOG, CDH-1, and Zeb-1 showed that the simulated microgravity environment led to expression patterns in MeT-5A cells similar to those observed in BR95 cells." (PMID 39451527, 2024). "Moreover, they reported that NANOG expression correlated with deep myometrial invasion, a higher cancer grade, and a positive lymph node status, all of which indicated a worse prognosis." (PMID 38539419, 2024). "Research studies in various cancers have shown over-expression of NANOG." (PMID 38558704, 2024). "Mechanistically, NSDHL knockdown impaired the cancer stemness characteristics of BCSCs by suppressing TGF-β signaling, which in turn decreased the secretion of TGF-β 1 and TGF-β3, inactivated Smad2 and Smad3, and downregulated the expression of SOX2 and NANOG, key regulators of cancer stemness." (PMID 39516821, 2024). "In addition, the overexpression of various downstream signaling involved in cancer initiation and progression, appears to originate from uncontrolled and abnormal NANOG expression." (PMID 38846985, 2024). "We identified BMI1, MYC, NANOG, and OCT3/4 (POU5F1 gene) pluripotency markers as the most prominent transcription factors associated with HDAC2 gene expression, highly supporting HDAC2’s association with cancer stemness." (PMID 39063083, 2024). "Similarly, the population of ALDH+ and NANOG-GFP+ CSCs in KLF8 overexpressing cancer cells was significantly increased compared to control cells." (PMID 37152043, 2023). "Moreover, MDA‐MB‐231 cells grown in FN‐silk networks had high cancer stem cell markers (i.e., NANOG, OCT4, and SOX2), accompanied by an up‐regulation of genes associated with basement membrane degradation and invasiveness (i.e., HIF1α, ITGAV, and MMP14)." (PMID 37693069, 2023). "NANOG homeobox (NANOG), sex determining region Y-box 2 (SOX2), and OCT4, common regulators of stemness, could mediate cancer proliferation and metastasis, which are associated with poor overall survival and advanced disease stage." (PMID 36830834, 2023). "Paracrine HGF induces YAP nuclear translocation by binding c-MET, resulting in the crosstalk between CAFs and cancer cells that HGF/c-MET-mediated induces the expression of stemness pluripotency markers such as NANOG, OCT4, and SOX2 in PC cells, as well as increased self-renewal ability." (PMID 37173787, 2023). "Low expression of cancer-related genes, such as NANOG, and high expression of infection-related genes, such as OLFM4, could be predictive markers for the efficacy of eradication therapy." (PMID 36831547, 2023). "Finally, we demonstrated in a mouse xenograft model that targeting TAZ or NANOG inhibits cancer stemness and improves chemosensitivity in vivo." (PMID 36646707, 2023). "Upon activation by norepinephrine, ATF1 potentiates cancer stemness by coordinated trans-activation of both nuclear pluripotency factors MYC/NANOG and mitochondrial biogenesis regulators NRF1/TFAM, thereby orchestrating nuclear reprograming and mitochondrial rejuvenating." (PMID 37463926, 2023). "CAFs and STC1 could upregulate the expression of cancer stemness genes (NANOG, SOX2, and OCT4), and STC1-Ab treatment blocked the promoting effect of CAFs on the expression of stemness genes in HCC cells." (PMID 37004088, 2023). "As OCT4, SOX2, Myc, and NANOG transcription factors are essential for normal stem cell propagation, they may also support the existence of cancer stem cells." (PMID 36674511, 2023). "OCT-4 and NANOG are the major drivers of self-renewal ability in cancer stem cells." (PMID 37841922, 2023).
cancer (continued). "This suggests that NANOG high/FOXJ1 low are more akin to cancer stem cells, which may be more likely chemo-resistant and thereby less susceptible to chemotherapy, leading to poor prognosis." (PMID 36323878, 2023). "Higher resistance to cancer treatment has been linked to the presence of key regulators of strain self-renewal, including octamer-binding transcription factor 4 (OCT4), sex-determining region Y-box 2 (SOX2), and the Nanog homeobox (NANOG)." (PMID 36439901, 2022). "The validity of NANOG as a cancer stem cell marker was discussed." (PMID 36497144, 2022). "Moreover, the overexpression of KLF4, SOX2, and NANOG were found in several malignancies, and their expression levels were correlated with poor prognosis, advanced-stage cancer, and shorter patient survival." (PMID 36553636, 2022). "Furthermore, the homeobox-domain transcription factor NANOG, a key regulator of embryonic development and cellular reprogramming, is ubiquitously expressed in human cancers." (PMID 35962453, 2022). "Moreover, NANOG expression was reinitiated in various cancer stem cells, contributing to the stem cell-like state of the cancer cells." (PMID 36376495, 2022). "We also used cisplatin as a control for the NANOG/HDAC1 axis–independent cancer drug." (PMID 35104240, 2022). "Since CSC markers, LGR5 and NANOG have been shown to be progressively expressed during carcinogenesis and promote cancer cell proliferation and tumor formation, we next evaluated the impact of PCs repression in tumor cells on LGR5 and NANOG expression during tumor progression." (PMID 35267511, 2022). "The formation of this complex promotes the translation of the oncogene mRNA, causing cancer cells to acquire increased malignant tumor-forming capacity in vivo and increased protein levels of pluripotency factors OCT4, SOX2, NANOG and KLF4 (Kruppel-like factor 4)." (PMID 35954194, 2022). "Of note, OCT4 together with SOX2 and NANOG were reported to reprogram the cancer cells to cancer stem cells (CSCs) and serve as major transcription factors maintaining the stemness of CSCs, and calcification or/and osteogenesis were noted in various cancers." (PMID 36581839, 2022). "Knockdown of NANOG resulted in decreased expression of CD59 in the indicated cancer cells." (PMID 35606403, 2022). "It was proposed that NANOG might be considered as one of the markers, based on the following observations of multiple types of cancer cells, when NANOG is overexpressed." (PMID 36497144, 2022). "Indeed, X-ray photon irradiation resulted in an increase in cancer stem cells markers (CD44, CD133, OCT4, SOX2, and NANOG) and increased the pool of cancer stem cells in xenograft mouse models." (PMID 35740495, 2022). "Using the transcriptional data obtained from cancer patients treated with PD-1 therapy and a newly established murine preclinical anti-PD-1 therapy-refractory model, NANOG was identified as a factor that enhanced patients’ resistance to immune-checkpoint inhibitors." (PMID 36497144, 2022). "These include ALDH1, ABCG2, CD44, CD133, NANOG, and SRY-box transcription factor 2 (SOX2), all of which have been linked to chemoresistance in a number of first line anti-cancer therapies—for example, axitinib is an oral, potent, small molecule ATP-competitive multitarget tyrosine kinase inhibitor." (PMID 36338714, 2022). "Similarly, gene expression of other cancer stemness markers NANOG, SOX2, and OCT4 in HepG2 cells was also increased significantly." (PMID 36411463, 2022). "The patient-derived spheroid cultures of TGCT cells that we used in the present study initially exhibit a characteristic of cancer stem-like cells (CSCs) because the model abundantly expressed CSC markers such as NANOG and SOX2, and the TGCT cultures can be easily applied to in vivo models." (PMID 36319719, 2022). "Therefore, we have provided proof of the principle that NANOG inhibition is an effective strategy to control human cancer, particularly in the context of antibody-based therapy." (PMID 35606403, 2022).